DOC2A (double C2 domain alpha)
Description:
Calcium sensor which most probably regulates fusion of vesicles with membranes. Binds calcium and phospholipids. May be involved in calcium dependent neurotransmitter release through the interaction with UNC13A. May be involved in calcium-dependent spontaneous release of neurotransmitter in absence of action potentials in neuronal cells. Regulates Ca(2+)-dependent secretory lysosome exocytosis in mast cells.
Synonyms: Doc2
Tractability: Antibody: UniProt places it where antibodies can reach, with high confidence. PROTAC: ubiquitination databases record sites on it.
Gene: Protein-coding gene on chromosome 16 (30,005,507 to 30,023,270, reverse strand). Ensembl gene ENSG00000149927.
Subcellular location: Lysosome; Cytoplasmic vesicle, secretory vesicle, synaptic vesicle membrane; Synapse, synaptosome
Subcellular location (Human Protein Atlas): Cell Junctions; Nucleoli; Nucleoplasm
Gene Ontology:
Molecular function: protein binding
Biological process: regulation of calcium ion-dependent exocytosis; calcium-dependent activation of synaptic vesicle fusion; chemical synaptic transmission; nervous system development; positive regulation of calcium ion-dependent exocytosis; synaptic vesicle exocytosis
Cellular component: extrinsic component of synaptic vesicle membrane; synapse; glutamatergic synapse; lysosome; membrane; synaptic vesicle membrane
Genetic constraint (gnomAD): Loss-of-function variants: 32 observed, 44.15 expected, observed/expected ratio (o/e) 0.72, 90% interval 0.55 to 0.97. The upper end of that interval is the gene's LOEUF score, 0.97, which puts it in group 4 of 6, group 1 being the genes least tolerant of losing a copy. Missense variants: 474 observed, 559.48 expected, observed/expected ratio (o/e) 0.85, 90% interval 0.79 to 0.91. Synonymous variants: 241 observed, 233.71 expected, observed/expected ratio (o/e) 1.03, 90% interval 0.93 to 1.15.
Homologues: Orthologues: chimpanzee DOC2A (99% identical), macaque DOC2A (98% identical), pig DOC2A (96% identical), dog DOC2A (96% identical), guinea pig DOC2A (96% identical), mouse Doc2a (95% identical), rat Doc2a (93% identical), rabbit DOC2A (80% identical), tropical clawed frog doc2a (70% identical), zebrafish doc2a (66% identical). Paralogues in human: DOC2B (64% identical), RPH3A (54% identical), SYT1 (28% identical), SYT2 (28% identical), SYT5 (28% identical), SYT3 (26% identical), SYT6 (26% identical), SYT17 (26% identical), SYT7 (26% identical), SYT9 (25% identical), SYTL4 (25% identical), SYT10 (24% identical), and 19 more.
Diseases named in the same sentence as DOC2A in open-access papers:
DOC2A is named in the same sentence as 22 diseases in open-access papers, as found by Europe PMC text mining. Sharing a sentence is not in itself a finding about the gene and the disease. The quoted sentences say what the papers report.
schizophrenia (6 papers, 2020 to 2025). A major psychotic disorder characterized by abnormalities in the perception or expression of reality. "DOC2A and MAPK3, encoding double C2 domain alpha and mitogen-activated protein kinase 3, respectively, map to 16p11.2, duplication of which is associated with schizophrenia." (PMID 31691811, 2020). "DOC2A is mainly expressed in the brain and thought to be linked to Ca(2+)-dependent neurotransmitter release and has been previously linked to schizophrenia, a psychiatric disorder, in part, characterized by disorded cognitive functioning." (PMID 30867560, 2020). "GRM8, like DOC2A, has been linked to schizophrenia in addition to sporadic Creutzfeldt–Jakob disease risk." (PMID 30867560, 2020).
autism (2 papers, 2013 to 2021). Persistent deficits in social interaction and communication and interaction as well as a markedly restricted repertoire of activity and interest as well as repetitive patterns of behavior. "For example, two genes within the autism-associated 16p11.2 region, SEZ6L2 and DOC2A, as well as the febrile seizure-associated gene STX1B, were downregulated in carriers of the 16p12.1 deletion." (PMID 34657631, 2021).
epilepsy (2 papers, 2013 to 2026). A brain disorder characterized by episodes of abnormally increased neuronal discharge resulting in transient episodes of sensory or motor neurological dysfunction, or psychic dysfunction. "Nonetheless, given the high scores of both DOC2A and TAOK2, it is not unreasonable to hypothesize that one or more other genes in the region might also contribute to the epilepsy seen in these subjects." (PMID 24086149, 2013).
breast carcinoma (1 paper, 2020). "Noteworthy was that a handful of genes from this network had been annotated as TSGs either specifically in relation to breast cancer (GATA3, RERG, and SIAH2) or in other types of cancer (DOC2A and RGS22)." (PMID 32605588, 2020).
cardiac dysrhythmias (1 paper, 2024). "Two genes (DOC2A and PHB) reached GWS for AD and cardiac dysrhythmias." (PMID 39201500, 2024).
cognitive decline (1 paper, 2025). "DOC2A encodes a calcium-sensor protein essential for synaptic vesicle priming and neurotransmitter release, with variants linked to cognitive decline in AD." (PMID 41573740, 2025).
colorectal cancer (1 paper, 2016). A primary or metastatic malignant neoplasm that affects the colon or rectum. "Since DOC2A has been reported as a suppressor gene in many carcinomas such as colorectal cancer and urothelial cancer, we suggest AHR might promote glioma progression through inhibiting the tumor suppressor gene, DOC2A." (PMID 27586240, 2016).
type 2 diabetes (1 paper, 2024). "Colocalisation analyses between GTEx v7 and DIAMANTE type 2 diabetes GWAS signals revealed 22 genes colocalised (posterior inclusion probability (PIP) >0.85) in the pancreas, with only DOC2A also implicated by our Capture-C approach." (PMID 39240351, 2024).
cancer (3 papers, 2016 to 2023). A tumor composed of atypical neoplastic, often pleomorphic cells that invade other tissues. "Data from the PPI network showed that ASPHD1 is related to several proteins and genes such as KIF22, INO80E, SEZ6L2, and DOC2A, most of which are cancer-related." (PMID 37686578, 2023).
tumor (2 papers, 2016 to 2020). "Some genes in this module were connected by processes proposed to be involved in tumor progression, such as DOC2A, CGN (Cingulin), PARD6B, NEDD4L, and SYT9 which belonged to the KEGG pathway, tight junction (TJ) (hsa04530), and GEO term, cell junctions (GO:0030054)." (PMID 32605588, 2020).
DOC2A also shares sentences with these, for which no sentence is quoted: alcohol use disorder (1 paper); Alzheimer disease (1); amyotrophic lateral sclerosis (1); bipolar disorder (1); generalized epilepsy (1); glioma (1); Intellectual disability (1); Lewy body dementia (1); Obesity (1); Parkinson disease (1); psychiatric disorder (1); renal carcinoma (1).